FANCD2 (FA complementation group D2)
Diseases named in the same sentence as FANCD2 in open-access papers (continued):
Sharing a sentence is not in itself a finding about the gene and the disease.
breast carcinoma (54 papers, 2005 to 2025). "There is also an association between BRCA2 loss and increased FANCD2 mRNA levels in breast cancer cell lines and tumors." (PMID 40669753, 2025). "This contrasts with MM1 domain mutations identified in non-BRCA1/2 breast cancer families, which show the opposite pattern-disrupted FANCD2:FANCI monoubiquitination but intact ATPase activity." (PMID 40447800, 2025). "A study conducted in Finland supports these findings by showing a significant association of variant (c.2715 + 1G > A) in the FANCD2 gene with breast cancer." (PMID 39051418, 2024). "In contrast, the upregulation of FANCD2 was positively associated with tumor size and a poor prognosis in breast cancer, ovarian cancer, nasopharyngeal carcinoma, glioblastoma, endometrial carcinoma, and esophageal squamous cell carcinoma." (PMID 34743173, 2021). "Several previous studies have shown that FANCD2 is closely associated with several cancer types, including breast cancer, hepatocellular carcinoma and leukemia." (PMID 33778001, 2021). "It’s reported that FANCD2 was highly expressed in BRCA1/2-mutated breast cancer, ovarian cancers and uterine cancers." (PMID 32563252, 2020). "Overexpression of FANCD2 is positively associated with tumor size and poor prognosis in breast cancer, ovarian cancer, nasopharyngeal carcinoma, glioblastoma, and endometrial carcinoma." (PMID 32906798, 2020). "Published targeted next-generation sequencing (NGS) analyses show that germline FANCD2 variants are associated with breast cancer and head and neck squamous cell carcinoma (HNSCC) susceptibility." (PMID 32906798, 2020). "Tissue microarray analysis showed that upregulation of FANCD2 is positively associated with tumor size and adverse prognosis in breast cancer, ovarian cancer, nasopharyngeal carcinoma, glioblastoma, and endometrial carcinoma." (PMID 32906798, 2020). "In Helsinki, the FANCD2 mutation was identified in four breast cancer cases in the genotyped hereditary cohort (diagnosed at the age of 41, 44, 49 and 68, respectively)." (PMID 28386063, 2017). "In conclusion, truncating variants in TEX15 and FANCD2 are potential breast cancer risk factors, warranting further investigations in other populations." (PMID 28386063, 2017). "For instance, large deletions of VHL and C3orf10, as well as BRK1, have been associated with lower lifetime risk of kidney cancer, whereas the deletion encompassing VHL and the FANCD2 gene may be linked to an increased susceptibility to breast cancer." (PMID 39336783, 2024). "Low levels of Fancd2 ubiquitination can be a diagnostic indicator of FA and correlate with shorter time of disease-free survival in the context of sporadic breast cancer." (PMID 35595243, 2022). "In addition, FANCD2 genes were correlated with the diagnostic and prognostic factors of low-grade glioma and breast cancer." (PMID 35309947, 2022). "Due to the DNA translocase activity, SMARCAL1, a member of SNF2 family, could reverse the nascent DNA degradation induced by FANCD2 deficiency in BRCA1/2-mutated breast cancer cells." (PMID 32563252, 2020). "FANCD2 overexpression conferred resistance to PARPi in BRCA1/2-mutated breast cancer cell lines." (PMID 32563252, 2020). "Further studies are needed to investigate whether FANCD2-related breast cancers are similar to those seen BRCA2 mutation carriers." (PMID 25093046, 2014). "Our study suggests that a deletion of FANCD2 gene, an important gene in the DNA repair pathway, may be associated with an increased risk of breast cancer, but further studies are needed in this regard." (PMID 25093046, 2014). "In our present study, gene silencing of FANCF in MCF-7 and T-47D breast cancer cells blocked the FA/BRCA pathway as evidenced by reducing the level of FANCD2 mono-ubiquitination, the loss of FANCD2 foci, inhibiting cell proliferation, promoting apoptosis and DNA damage." (PMID 22952942, 2012). "However, 10–20% of breast cancer patients also show loss of FANCD2 expression." (PMID 33662042, 2021).
breast carcinoma (continued). "Therefore, FANCD2 is good candidate for breast cancer susceptibility gene." (PMID 25093046, 2014). "To provide functional evidence that STAT3 inhibition is sufficient to render cells deficient in FA pathway activity, we tested the melphalan sensitivity of breast cancer cells invalidated for STAT3 expression versus cells invalidated for FANCD2 expression." (PMID 40038300, 2025). "In a Chinese study, poor prognosis was observed in sporadic breast cancer patients with high levels of FANCD2." (PMID 39051418, 2024). "Further analysis using the CPTAC database showed a significant increase in FANCD2 protein expression in breast cancer, RCC, UCEC, LUSC, LIHC, and GBM." (PMID 38443946, 2024). "Elevated FANCD2 expression acts as an independently unfavorable prognostic factor, exhibiting a positive correlation with tumor size and stage in spontaneous breast cancer." (PMID 38443946, 2024). "It is noteworthy that BRCA1 and FANCD2 mutation carriers commonly have KRT14-positive breast tumors and among sporadic breast cancer patients those with KRT14-positive tumors have markedly poorer prognosis than the patients with KRT14-negative tumors." (PMID 38597967, 2024). "The FA pathway has been associated with PARP inhibitor resistance in head and neck cancers, and the overexpression of FANCD2 confers PARP inhibitor resistance in BRCA1/2 mutant breast cancer cells." (PMID 35999268, 2022). "FANCD2 was a sensitive and independent prognostic factor for breast cancer, and its overexpression is a reliable indicator of lymph node metastasis in colorectal cancer." (PMID 34778244, 2021). "Additional experiments will be necessary to properly demonstrate impaired end-joining DNA repair in everolimus-treated tumors and to validate FANCD2 as a key component of the cross-talk between mTOR and DNA repair in breast cancer." (PMID 30038706, 2018). "Further studies on additional Finnish breast cancer cohorts (both unselected and hereditary) identified more FANCD2 c.2715 + 1G > A carriers, but the frequency remained low, which is typical for mutations causative of FA25." (PMID 28386063, 2017). "In our study, breast cancers seen in carrier of a deletion of FANCD2 gene were invasive, grade 2 ductal carcinomas." (PMID 25093046, 2014). "FANCD2 (12th) interacts with the BRCA1 and BRCA2 genes in the DNA repair process to reduce the risk of breast cancer." (PMID 24564336, 2014). "FANCF silencing by FANCF-shRNA blocked functions of FA/BRCA pathway through inhibition of FANCD2 mono-ubiquitination in breast cancer cell lines MCF-7 and T-47D." (PMID 22952942, 2012). "For example, Fanconi anemia gene Fancd2 and breast cancer gene Brca2 had a higher expression in testis than in ovary." (PMID 18522719, 2008). "We sought to carry out mutation analysis of FANCD2, BRIP1/BACH1, LMO4 and SFN in a large number of non-BRCA1/2 breast cancer families." (PMID 16280053, 2005). "Reduced levels of FANCA and FANCD2 in AML and breast cancer, respectively, have also been reported, although the causes of these reduced FANCA and FANCD2 levels remain unknown." (PMID 34884777, 2021). "High FANCD2 expression correlated with poor breast cancer patients’ outcomes." (PMID 33662042, 2021). "The extensive case-control association analysis performed here for the rare, presumably deleterious alleles in genes encoding important players in the DDR pathway identified two potentially breast cancer predisposing mutations: TEX15 c.7253dupT and FANCD2 c.2715 + 1G > A." (PMID 28386063, 2017). "We therefore hypothesized that germline mutations in the BRCA1-interacting genes, FANCD2, BRIP1/BACH1, LMO4 and SFN, may account for some non-BRCA1/2 multiple-case breast cancer families." (PMID 16280053, 2005). "In addition, we screened a further 399 and 253 cases, respectively, for specific regions of the FANCD2 and BRIP1/BACH1 genes that contained functionally important domains, or variants previously found in the germline of breast cancer cases." (PMID 16280053, 2005).
breast carcinoma (continued). "We hypothesized that germline mutations in FANCD2, BRIP1/BACH1, LMO4 and SFN may account for some of the unexplained multiple-case breast cancer families." (PMID 16280053, 2005). "In addition, two studies have investigated the relationship between FANCD2 and breast cancer." (PMID 39051418, 2024). "Primary cancers have been observed in Fanca, Fancm, Fancf, Fancd1, and Fancd2 mutant mice, including ovarian adenocarcinomas, hepatocellular carcinomas, lymphomas, ovarian granulosa cell tumors, spindle-cell sarcomas, lung carcinomas, breast cancers, and histiocytic sarcomas." (PMID 36685883, 2022). "Of note, two of the studied mutations were also simultaneously identified in Helsinki: FANCD2 c.2715 + 1G > A in clinical panel sequencing of a patient with early onset triple-negative breast cancer and RNF168 c.640_644del5 in exome sequencing of hereditary breast cancer patients." (PMID 28386063, 2017). "In another study, 399 women, from 356 non-BRCA1/2 breast cancer families (some had more than one index case because multiple women were affected at the same age), were screened for FANCD2 mutations by DHPLC/sequencing and no pathogenic mutations were identified." (PMID 25093046, 2014). "Four proteins (FANCD2, EEF1A1, YWHAE, PGLS) have PPIs with at least one protein in all signatures and one protein in the breast cancer signature (ALDOC) interacts with all other four signatures." (PMID 36329531, 2022). "The FA genes we identified as DEGs; CENPX, FAAP24, FANCD2, FANCI, UBE2T and FANCA are all overexpressed in breast cancer." (PMID 33662042, 2021). "Next, the expression level of two FA/BRCA genes, FANCD2 and FANCI, was confirmed by qPCR and western blot in PAK1 depleted human breast cancer cells." (PMID 27740936, 2016). "It appears unlikely, therefore, that FANCD2, BRIP1/BACH, LMO4 and SFN account for more than a small proportion of inherited forms of breast cancer." (PMID 16280053, 2005). "FANCD2 is highly overexpressed in BRCA1/2 mutant breast cancers and contributes to DNA fork stability by inhibiting MRE11-mediated DNA replication fork degradation in BRCA1/2 mutant breast cancer cells." (PMID 37892162, 2023). "Mutation analysis of the BRCA1-interacting genes FANCD2, BRIP1/BACH, LMO4 and SFN in a large number of non-BRCA1/2 breast cancer families did not identify any highly penetrant, pathogenic mutations." (PMID 16280053, 2005). "A previous study of familial breast cancer cases did not identify mutations in FANCA, C, D2, E, F, G, so at present it remains unclear whether FANCC, which acts upstream of FANCD2, is a breast cancer predisposing gene." (PMID 18786261, 2008). "However, in breast cancer, FANCD2 staining was demonstrated to be predictive independent of Ki67." (PMID 39768544, 2024). "The expression of two FA genes, FANCD2 and FANCI, was confirmed by qPCR and western blot in PAK1 depleted human breast cancer cells with or without PAK1 amplification and/or overexpression." (PMID 27740936, 2016).
anemia (37 papers, 2008 to 2025). A reduction in the number of red blood cells, the amount of hemoglobin, and/or the volume of packed red blood cells. "Fanconi anemia-associated gene, Fanconi anemia complementation group D2 (FANCD2), plays a key role in DNA inter-strand crosslinks repair upon stress." (PMID 35754466, 2022). "Fanconi anemia complementation group D2 (FANCD2) has been reported to serve as a ferroptosis-associated gene and has a close relationship with tumorigenesis and drug resistance." (PMID 36246623, 2022). "This mutation lies in the binding domain of the Fanconi anemia complementation group D2 (FANCD2) and CG (FANCG) proteins; thus interactions with these proteins may be impaired." (PMID 30040829, 2018). "Also in the signature were genes encoding the DNA glycosylase NEIL3, Fanconi Anemia factors (FANCD2, UBE2T), the ubiquitin protein ligase UBE3B, and two specialized DNA polymerases, POLM and POLQ, involved in the non-homologous end-joining (NHEJ) pathways of DSB repair." (PMID 34067180, 2021). "In the current study, the upregulation of Fanconi anemia complementation group D2 (FANCD2) was identified, which is reported as a crosslink repair gene." (PMID 40428293, 2025). "We noticed that the protein level of Fanconi anemia complementation group D2 (FANCD2) is induced when cells are treated with increasing amounts of Mitomycin C (MMC), an ICL inducing agent." (PMID 41053315, 2025). "A recent study demonstrated that HES1 acts in concert with a Fanconi anemia protein, FANCD2 to suppress inflammation-induced PPARg to prevent HSC exhaustion." (PMID 39075526, 2024). "Fancl is a member of the Fanconi Anemia core complex with a plant homeodomain (PHD) that mono-ubiquitinates Fancd2 and Fanci." (PMID 38451917, 2024). "The ferroptosis-related gene Fanconi anemia complementation group D2 (FANCD2) is a suppressor of ferroptosis and plays an essential role in cell cycle progression, replication, and repair." (PMID 37821996, 2023). "FANCD2, a class of Fanconi anemia protein, participates in endonucleolytic notch, HR pathway, and translation synthesis, thereby maintaining DNA damage repair and genome stability." (PMID 37369808, 2023). "In contrast, Aldh2−/− Fancd2−/− mice survive longer (median 145 days) and develop anemia and cytopenia beyond 10 weeks of age." (PMID 37348497, 2023). "More recently, it has been reported that in lung cancer cells, RPS27L physically binds Fanconi anemia group D2 (FANCD2) and Fanconi anemia group I (FANCI), two proteins involved in DNA damage and repair." (PMID 34071057, 2021). "A key signalling step of the FA pathway is the mono-ubiquitination of Fanconi Anaemia Complementation Group D2 (FANCD2), which is achieved by the multi-subunit E3 ligase complex." (PMID 32409752, 2020). "FANCD2, a member of the Fanconi Anemia (FA) protein family, plays a vital role in DNA damage repair." (PMID 32957974, 2020). "CASIN inhibited mono-ubiquitination of Fanconi anemia (FA) complementation group D2 (FANCD2) of the FA DNA damage repair pathway in melphalan-resistant but not melphalan-sensitive cells, thereby sensitizing melphalan-resistant cells to DNA damage." (PMID 31632904, 2019). "Fanconi anemia (FA) proteins play pivotal roles in cellular responses to DNA damage and Fance acts as a molecular bridge between the FA core complex and Fancd2." (PMID 27486799, 2016). "Under normal conditions, the monoubiquitination of Fanconi Anemia (FA) group D2 protein (FANCD2) occurs in each S-phase of cell cycle, which is the basal level of FANCD2 monoubiquitination." (PMID 24658369, 2014). "Moreover, it has been shown previously that the Fanconi anemia protein FANCD2 interacts with COUP-TF2 and TR4 to promote ALT activity in ALT cells." (PMID 38752489, 2024). "Fanconi anemia complementation group D2 (FANCD2) is a vital gene that regulates ferroptosis." (PMID 37821996, 2023).
anemia (continued). "The majority of Aldh2−/− Fancd2−/− mice at this age exhibit significantly reduced number of Lineage− [Lin−] c-Kit+ Sca-1+ (LKS) HSPCs but can maintain sufficient blood production to prevent symptomatic anemia." (PMID 37348497, 2023). "Of note, Fancd2 null mutant mice exhibit a variety of phenotypes, including reduced body size, some degree of abnormal germ cells, eye abnormalities an increased incidence of tumors such as adenomas, and anemia, mirroring the anemia found in human FA patients." (PMID 35595243, 2022). "Moreover, the expression of Rad18, Fanconi anemia group D2 protein (FANCD2) and Fanconi anemia group J protein (FANCJ) proteins were also upregulated." (PMID 32365503, 2020). "In human cells Usp1 deubiquitylates PCNA as well as the Fanconi's anaemia protein FANCD2." (PMID 22829782, 2012). "We also found that several Fanconi anemia (FA) proteins (e.g., FANCA, FANCF, FANCM, FANCD2), which are central proteins of inter-strand crosslink (ICL) repair, favored MMEJ." (PMID 38909016, 2024). "Additionally, we found a clique that consists of Fanconi anemia (FA) proteins (FANCF, FANCM, FANCG and FANCD2) and a third clique with two FA proteins together with BLM and RMI2." (PMID 38909016, 2024). "Notably, Fancd2–/– Lnk–/– mice showed reduced myeloid and lymphoid expansion and amelioration of anemia compared with Lnk−/− mice, although we were not able to do a comprehensive study of the pathology of the moribund mice." (PMID 41165757, 2025).